SLBP (stem-loop histone mRNA binding protein)
Description:
RNA-binding protein involved in the histone pre-mRNA processing. Binds the stem-loop structure of replication-dependent histone pre-mRNAs and contributes to efficient 3'-end processing by stabilizing the complex between histone pre-mRNA and U7 small nuclear ribonucleoprotein (snRNP), via the histone downstream element (HDE). Plays an important role in targeting mature histone mRNA from the nucleus to the cytoplasm and to the translation machinery. Stabilizes mature histone mRNA and could be involved in cell-cycle regulation of histone gene expression. Involved in the mechanism by which growing oocytes accumulate histone proteins that support early embryogenesis (By similarity). Binds to the 5' side of the stem-loop structure of histone pre-mRNAs (By similarity).
Synonyms: HBP
Tractability: PROTAC: UniProt records ubiquitination sites on it; ubiquitination databases record sites on it; its protein half-life has been measured.
Gene: Protein-coding gene on chromosome 4 (1,692,731 to 1,712,344, reverse strand). Ensembl gene ENSG00000163950.
Subcellular location: Cytoplasm; Nucleus
Subcellular location (Human Protein Atlas): Nucleoli; Nucleoplasm; Cytosol
Pathways (Reactome):
Metabolism of RNA: SLBP Dependent Processing of Replication-Dependent Histone Pre-mRNAs; Transport of the SLBP Dependant Mature mRNA
Gene expression (Transcription): RNA Polymerase II Transcription Termination
Gene Ontology:
Molecular function: identical protein binding; mRNA binding; protein binding; RNA binding; histone pre-mRNA DCP binding; histone pre-mRNA stem-loop binding
Biological process: cap-dependent translational initiation; mRNA transport; mRNA 3'-end processing by stem-loop binding and cleavage
Cellular component: cytoplasm; cytosol; histone mRNA stem-loop binding complex; nucleolus; nucleoplasm; nucleus; histone pre-mRNA 3'end processing complex; ribonucleoprotein complex
Genetic constraint (gnomAD): Loss-of-function variants: 14 observed, 17.01 expected, observed/expected ratio (o/e) 0.82, 90% interval 0.54 to 1.29. The upper end of that interval is the gene's LOEUF score, 1.29, which puts it in group 5 of 6, group 1 being the genes least tolerant of losing a copy. Missense variants: 250 observed, 186.92 expected, observed/expected ratio (o/e) 1.34, 90% interval 1.21 to 1.49. Synonymous variants: 80 observed, 65.66 expected, observed/expected ratio (o/e) 1.22, 90% interval 1.02 to 1.47.
Homologues: Orthologues: macaque SLBP (99% identical), chimpanzee SLBP (94% identical), mouse Slbp (89% identical), rat Slbp (89% identical), dog SLBP (88% identical), guinea pig SLBP (84% identical), pig SLBP (84% identical), tropical clawed frog slbp (53% identical), zebrafish slbp (48% identical), Caenorhabditis elegans cdl-1 (30% identical), Drosophila melanogaster Slbp (28% identical).
Diseases named in the same sentence as SLBP in open-access papers:
SLBP is named in the same sentence as 21 diseases in open-access papers, as found by Europe PMC text mining. Sharing a sentence is not in itself a finding about the gene and the disease. The quoted sentences say what the papers report.
breast carcinoma (4 papers, 2022 to 2023). "miR-432 was downregulated in breast cancer tissues and functioned as a tumor inhibitor in breast cancer by targeting E2F3 or SLBP." (PMID 37303741, 2023). "Similar phenotypic changes of SLBP downregulation were observed upon the knockdown of 53BP1 in many human cell lines with the exception of three breast cancer cell lines." (PMID 35037047, 2022). "And lncRNA DRAIC was activated by FOXP3 in breast cancer and promoted cell proliferation in SKBR3 and MDA-MB-231 cells via sponging miR-432-5p to increase SLBP levels." (PMID 35992823, 2022). "And in breast cancer cell lines, lncRNA DRAIC was up-regulated by FOXP3 and promoted cell migration and invasion via the miR-432-5p/SLBP axis.Moreover, lncRNA DRAIC improved esophageal cancer Eca-109 and EC9706 cell invasion through binding to miR-149-5p, which regulated NFIB levels." (PMID 35992823, 2022).
adenoma (1 paper, 2024). A neoplasm arising from the epithelium. "The comparative analysis of the transcriptional profiles of NAGs and ACAs revealed the overexpression of specific genes in all adenomas compared to normal adrenals, including IGF2R, GAS2 and SLBP." (PMID 39167619, 2024).
adrenocortical tumours (1 paper, 2024). "However, the function of both GAS2 and SLBP in adrenocortical tumours remains to be further investigated." (PMID 39167619, 2024).
COVID-19 (1 paper, 2025). A disease caused by infection with severe acute respiratory syndrome coronavirus 2. "Together, our findings identify SLBP as a host protein that promotes SARS-CoV-2 frameshifting, highlighting its potential as a druggable target for COVID-19." (PMID 40514371, 2025).
myelogenous leukaemia (1 paper, 2022). "Using a ChIA-PET dataset we observed an interaction between the CpGs and a region including the 5′ end of SLBP and sequence downstream of TMEM129 in K562 cells, an immortalised myelogenous leukaemia cell line." (PMID 35941660, 2022).
osteosarcoma (1 paper, 2022). A usually aggressive malignant bone-forming mesenchymal neoplasm, predominantly affecting adolescents and young adults. "Interestingly, H4C11 mRNA was previously found to be polyadenylated in human osteosarcoma cells, following knockdown of SLBP, but not polyadenylated in other studies." (PMID 36447390, 2022).
type 2 diabetes (1 paper, 2025). "In type 2 diabetes, genes like ST18, SNAP91, and SLBP are more central in the network, showing their importance in dealing with ongoing metabolic stress." (PMID 40909129, 2025).
tumor (9 papers, 2017 to 2024). "In our study, high expression of WDR4, EIF4G1 and SLBP were significantly associated with a poor OS (p < 0.001) and increased tumor stem cell score in LUAD." (PMID 36226166, 2022). "Although these analyses are based on mRNA expression, they indicate the clinical significance of FEM1B and SLBP protein levels in tumour progression, which can be regulated by SCR." (PMID 39140134, 2024). "SLBP knockout undermined the tumor-promoting effect of miR-384 silencing in OS cell lines, indicating that downregulation of miR-384 promotes tumor growth by upregulating SLBP and activating the PI3K/Akt pathway." (PMID 39119480, 2024). "Key genes identified in this subtype included SLBP, MBD1, MINK1, DPH1, and CSNK1D, which are noted in existing literature for their roles in tumor malignancy and progression, thereby reinforcing the reliability of the ac4C score." (PMID 39648231, 2024).
cancer (7 papers, 2016 to 2025). A tumor composed of atypical neoplastic, often pleomorphic cells that invade other tissues. "Therefore, we propose that FEM1B and SLBP levels can potentially be used as markers to predict the prognosis of certain cancers." (PMID 39140134, 2024). "Expression of the mitochondria-related genes including SLBP, ARPC1A, and TOMM34 (TCGA database) were significantly higher in cancer tissues than the normal tissues." (PMID 39012280, 2024).
infection (2 papers, 2013 to 2024). The state of being infected such as from the introduction of a foreign agent such as serum, vaccine, antigenic substance or organism. "Among the 1,451 genes whose expressions were specifically altered in CEF after infection, some were involved in immune-related functions, while others, such as the significantly upregulated SLBP, P2RX7, GGT5, and RNF213, could promote viral particle replication or enhance the effect of infection." (PMID 38299864, 2024). "Although SLBP genes were not in the key KEGG pathway analysis, they were included as important because of their high differential expression as well as their pro-infection role as demonstrated in previous viral studies." (PMID 38299864, 2024).
genetic disorder (1 paper, 2017). "This clinically variable and complex genetic disorder is caused by a partial deletion of the distal part of chromosome 4 (4p16.3), which usually leads to a haploinsufficiency of stem-loop binding protein (SLBP)." (PMID 28125036, 2017).
SLBP also shares sentences with these, for which no sentence is quoted: microcephaly (3 papers); autoimmune disease (1); cholangiocarcinoma (1); colorectal cancer (1); glioblastoma (1); Lupus (1); non-small cell lung carcinoma (1); prostate carcinoma (1); Retinal coloboma (1); Wolf-Hirschhorn syndrome (1).